SMYD3 (SET and MYND domain containing 3)
Diseases named in the same sentence as SMYD3 in open-access papers (continued):
Sharing a sentence is not in itself a finding about the gene and the disease.
liver diseases (1 paper, 2020). "SMYD3 levels were higher in advanced liver disease (LC, HCC) compared to CHB, and HCC patients had higher SMYD3 levels than non-HCC patients." (PMID 32071406, 2020). "The present study aimed to investigate the association of VNTR polymorphisms in the SMYD3 promoter and SMYD expression with HBV infection and clinical progression of HBV-related liver diseases, in particular progression to HCC." (PMID 32071406, 2020). "In our study, SMYD3 serum levels were significantly increased according to the various HBV-related liver disease stages." (PMID 32071406, 2020). "However, patients with genotype VNTR 3/3 had increased SMYD3 serum levels according to the progression of liver diseases (HCC vs. CHB: P = 0.0005, LC vs. CHB: P = 0.036)." (PMID 32071406, 2020). "Levels of SMYD3 increased significantly according to the progression of liver diseases." (PMID 32071406, 2020). "SMYD3 serum levels increased according to clinical progression of liver diseases (P = 0.01); HCC patients had higher levels than non-HCC patients (P = 0.04)." (PMID 32071406, 2020).
lymphoma (1 paper, 2018). A malignant (clonal) proliferation of B- lymphocytes or T- lymphocytes which involves the lymph nodes, bone marrow and/or extranodal sites. "The most significant of these is the Smyd3 locus where intragenic insertions surrounding exons 6–8 are present to a significantly lesser extent in the late-stage lymphomas samples." (PMID 29985390, 2018).
malignant glioma (1 paper, 2021). A grade III or grade IV glioma arising from the central nervous system. "In summary, SMYD3 may play a role in the tumorigenesis of malignant glioma, but further mechanistic investigation is merited." (PMID 33637115, 2021).
microcephaly (1 paper, 2019). A congenital or acquired developmental disorder in which the circumference of the head is smaller than normal for the person's age and sex. "However, because ofthe presentation of microcephaly in the patients with intactAKT3 gene, the other candidate genes such as NLRP3,HNRNPU, SMYD3, and KIF26B have been suggestedto cause microcephaly." (PMID 31210441, 2019).
prostate adenocarcinoma (1 paper, 2023). "We also tested SMYD3 abundance in a genetically engineered mouse model that recapitulates the development of human lethal prostate adenocarcinoma and metastasis through MYC overexpression and loss of Pten in prostatic luminal epithelial cells (Hoxb13-MYC+/− Hoxb13-Cre+/−PtenFl/Fl, or BMPC mice)." (PMID 37976356, 2023). "The protein KMT SET and MYND domain 3 (SMYD3) is also highly expressed in PCa; however, whether it has a direct molecular role in promoting aggressive phenotypes associated with advanced prostate adenocarcinoma has not been clearly defined." (PMID 37976356, 2023).
prostate tumors (1 paper, 2023). "In total, these data indicate that SMYD3 expression is up-regulated in prostate tumors, particularly at advanced stages, implicating its misregulation in the progression of PCa." (PMID 37976356, 2023). "To investigate the involvement of SMYD3 in adhesion, we tested PCa cell adhesion to the extracellular matrix component fibronectin, self-adhesion, and adhesion to fibroblasts, which constitute a major component of the prostate tumor microenvironment." (PMID 37976356, 2023).
rectal tumors (1 paper, 2024). "Analyses of SMYD3-KO cells, drug-resistant cancer cell lines, patients’ residual gastric or rectal tumors that were resected after neoadjuvant therapy and mice models were performed." (PMID 38812026, 2024). "The generation of an oxaliplatin-resistant CRC cell line and the analysis of patients’ residual gastric or rectal tumors that were resected after neoadjuvant therapy revealed a significant increase in SMYD3 protein levels in resistant samples." (PMID 38812026, 2024).
respiratory syncytial virus infection (1 paper, 2017). "H3K4 methyltransferase Smyd3 has been shown to target Foxp3 promoter region to increase its expression, promote iTreg cell development and protect mice from exacerbated inflammation during respiratory syncytial virus infection by a TGF-β-Smad3-dependent mechanism." (PMID 28598443, 2017).
serous carcinoma (1 paper, 2024). "The analysis revealed that the expression level of SMYD3 was significantly increased in EC tissues compared with normal controls, as well as endometrioid, serous carcinoma or mixed serous and endometrioid." (PMID 38191478, 2024).
Splenomegaly (1 paper, 2025). Abnormal increased size of the spleen. "We also found that tumorigenesis associated with G600 cells resulted in splenomegaly, which was reversed by the disruption of either Smyd3 or Shcbp1." (PMID 40157910, 2025).
steatosis (1 paper, 2020). Increased lipid within the cytoplasm of cells. "The hepatocyte steatosis model studies showed that knocking down SMYD3 led to significantly decreased HMGCR promoter activity." (PMID 31968646, 2020). "In the present study, using mice with type 2 diabetes mellitus (T2DM) and a hepatocyte steatosis model, the effects of COS on gut microflora and the SMYD3-mediated transcriptional regulation of HMGCR were investigated." (PMID 31968646, 2020). "Furthermore, using an oleic acid-induced hepatocyte steatosis model, we found that HMGCR can be directly transactivated by SET and MYND domain containing 3 (SMYD3), a transcriptional regulator, via 5′-CCCTCC-3′ element in the promoter." (PMID 31968646, 2020).
tauopathy (1 paper, 2023). Neurodegenerative disorders involving deposition of abnormal tau protein isoforms (tau proteins) in neurons and glial cells in the brain. "Inhibiting Smyd3 or knockdown of Fbxo2 rescues synaptic and cognitive deficits in the mouse model of tauopathies." (PMID 36609445, 2023). "Here we find that the histone methyltransferase Smyd3, which catalyzes histone H3 lysine 4 trimethylation (H3K4me3) to activate gene transcription, is significantly elevated in prefrontal cortex (PFC) of AD patients and P301S Tau mice, a model of tauopathies." (PMID 36609445, 2023).
Theileria infection (1 paper, 2014). "Moreover, Theileria infection is known to induce AP-1-driven mmp9 expression via induction of the methyltransferase SMYD3 that promotes trimethylation of histone H3K4 (H3K4me3) at the mmp9 promoter." (PMID 25375322, 2014).
type 2 diabetes mellitus (1 paper, 2020). A type of diabetes mellitus that is characterized by insulin resistance or desensitization and increased blood glucose levels. "In summary, this paper was the first to find that SMYD3 can regulate glycolipid metabolism enzymes such as HMGCR and plays an important role in diabetes." (PMID 31968646, 2020).
cancer (118 papers, 2006 to 2025). A tumor composed of atypical neoplastic, often pleomorphic cells that invade other tissues. "Three unrelated protein targets linked to cancer or inflammation (SMYD3, NUDT5, and PHIP) were selected." (PMID 39966348, 2025). "First, we investigated the effects of SMYD3 on cancer cell proliferation by a loss-of-function assay." (PMID 38191478, 2024). "More particularly, SMYD3 is frequently overexpressed in human cancers, and its high expression is associated with poor prognosis." (PMID 38148333, 2024). "SMYD3 oncogenic activity has been linked to cancer progression through multiple mechanisms, including the interaction with and methylation of non-histone proteins." (PMID 38812026, 2024). "In this section, we describe SMYD3-mediated regulatory mechanisms that are implicated in the progression of several cancers, including mechanisms that regulate cancer cell proliferation, metastasis, and drug resistance." (PMID 39482529, 2024). "Overexpression of SMYD3 has been associated with poor tumor prognosis and is being pursued as a therapeutic target for cancer." (PMID 38540216, 2024). "Aberrant SMYD3 expression is associated with carcinogenesis, and evidence indicates that it is involved in promoting the expression of critical oncogenes in cancer, including breast, colorectal, gastric, liver, and ovarian cancers." (PMID 39482529, 2024). "Abnormal SMYD3 expression has been reported in various cancers, and SMYD3 upregulation is associated with drug resistance." (PMID 39482529, 2024). "Numerous previous studies have reported that SMYD3 is upregulated in several cancers; therefore, SMYD3 is closely associated with disease progression." (PMID 39482529, 2024). "As a SET domain-containing methyltransferase, SMYD3 has been implicated in various cellular functions and is upregulated in several cancers." (PMID 38191478, 2024). "This schematic diagram provides a general overview of the complexity of SMYD3 functions in the framework of cancer-associated processes." (PMID 37954147, 2023). "Since then, SMYD3 has been linked to the tumorigenic cascade for various types of cancer in which methyltransferase activity is dysregulated." (PMID 36838987, 2023). "The SMYD3 interactor mTOR is involved in the “avoiding immune destruction” cancer hallmark, and its signaling is a key regulator of immune cell metabolism and function." (PMID 37998381, 2023). "SMYD3 is also implicated in cancer progression as it can methylate chromosomal histones, thereby regulating tumor proliferation, apoptosis, invasion, and metastasis." (PMID 36816359, 2023). "Among them, SMYD3 is a SET domain-containing protein that has histone methyltransferase activity on histone H3K4, and SMYD3 is frequently overexpressed in different cancer cell types, which is associated with advanced stage and poor survival." (PMID 37179342, 2023). "The lysine methyltransferase SET and MYND domain 3 (SMYD3) methylates MAPK kinase kinase 2 (MAP3K2) in some cancers, causing enhanced activation of MAPK signaling." (PMID 37976356, 2023). "To focus our analysis on putative SMYD3 interactors playing a role in cancer, we analyzed specific protein clusters based on their involvement in each cancer hallmark." (PMID 35495117, 2022). "A significant benefit of this strategy is that our tripeptides can be used to develop pharmacological inhibitors of SMYD3 oncogenic PPIs in order to modify the composition of relevant multiprotein complexes associated with cancer driver proteins." (PMID 36496998, 2022). "In the present study, 22 HMT genes related to cancer development were first selected according to current literature, and it was found that high SMYD3 expression was significantly associated with poor progression-free survival in patients with DLBCL." (PMID 36057625, 2022).
cancer (continued). "To assess SMYD3 involvement in the “enabling replicative immortality” cancer hallmark, we analyzed in silico the corresponding Telomere Maintenance Reactome pathway (Id: R-HSA-157579.5), which comprises 93 proteins, 28 of which contain P-tripeptides." (PMID 35495117, 2022). "Here, we describe an innovative in silico methodology that allowed us to identify novel protein–protein SMYD3 interactions implicated in cancer pathways." (PMID 35495117, 2022). "In order to identify novel potential SMYD3 interactors related to the “deregulating cellular energetics” cancer hallmark, we analyzed in silico the comprehensive Metabolism Reactome pathway (Reactome Id: R-HSA-1430728.10), which comprises 2,146 proteins." (PMID 35495117, 2022). "Remarkably, we identified mTOR, BLM, MET, AMPK, and p130 as new SMYD3 interactors implicated in cancer processes." (PMID 35495117, 2022). "Upregulation of SMYD3 has been identified in several types of cancer, such as breast and colorectal cancer, and is associated with tumor proliferation and metastasis." (PMID 36057625, 2022). "Further studies are needed to gain insight into the functional mechanisms underlying these novel SMYD3 interactions in cancer hallmarks." (PMID 35495117, 2022). "Based on this in silico evidence and on the crucial role of AMPK as a major energetic sensor in cancer metabolism, we considered it the most relevant candidate for SMYD3 interaction in the “deregulating cellular energetics” cancer hallmark." (PMID 35495117, 2022). "Here, we focused on SMYD3 involvement in tumors related to the GI compartment, where its altered expression has been found linked to cancer initiation, progression and aggressiveness." (PMID 34503239, 2021). "Firstly, SMYD3 is implicated in cell cycle checkpoint control, through which it induces a high rate of cell division, which is typical of cancer cells." (PMID 34503239, 2021). "Since SMYD3 regulates several key cancer-associated proteins through direct interaction, we carried out an in silico peptide screening with the aim of identifying new SMYD3 interactors to better characterize its involvement in cancer progression." (PMID 34503239, 2021). "It has been reported that overexpressed SMYD3 regulates cell growth by causing an acceleration of cancer cell division through modulation of the cell cycle." (PMID 34503239, 2021). "This presents a direct biological link between SMYD3 expression and RAS mutations, and nominates SMYD3 as a drug target for RAS‐driven cancers." (PMID 33769711, 2021). "SET and MYN-domain containing 3 (SMYD3) is a chromatin modifier that has been implicated in the development and progression of various cancer types." (PMID 33637115, 2021). "Methylation of MAP3K2 by SMYD3 has been implicated in Ras-driven tumorigenesis, which makes SMYD3 a potential target for cancer therapy." (PMID 34281237, 2021). "Specifically, SMYD3 over-expression is highly associated with cancer development by regulating tumor proliferation, metastasis, invasion, and apoptosis." (PMID 33333978, 2020). "Overexpression of SMYD3 results in increased cell proliferation and activates many genes associated with cancer cell transformation and metastasis." (PMID 33333978, 2020). "Previous studies indicated that Smyd3 was elevated in cancer-associated phenotypes through methylation of histones (H3K4, H4K5 and H2A.Z) and non-histone proteins." (PMID 33144524, 2020). "SMYD3 is a histone methyltransferase that activates the expression of oncogenes or cell-cycle associated genes, resulting in a proliferation of cancer cells." (PMID 32050423, 2020). "Previous studies indicate that Smyd3 can regulate cancer‐associated phenotypes through its enzymatic activities including methylation of histones (such as H3K4, H4K5, and H2A.Z) and non‐histone proteins (such as VEGFR and MAP3K2)." (PMID 32779886, 2020).
cancer (continued). "Here we summarize SMYD3-mediated regulatory mechanisms, which are implicated in the pathophysiology of cancer, as drivers of distinct oncogenic pathways." (PMID 31935919, 2020). "SET and MYND domain-containing protein 3 (SMYD3) is a histone methyltransferase that has been implicated in cancer pathogenesis and acts as a gene transcriptional regulator." (PMID 31417652, 2019). "The available data also emphasize potential functional associations between SMYD3 and its interactors in normal physiology in addition to cancer." (PMID 31737645, 2019). "For instance, SMYD3 has been implicated in the differentiation of T regulatory cells, which regulate immune checkpoints in cancer." (PMID 29856759, 2018). "Among the SMYD enzymes, SMYD2 and SMYD3 have been implicated as targets for a variety of cancer indications." (PMID 29856759, 2018). "SMYD3 encodes for an H3-Hk histone methyltransferase that has been associated with increased cell proliferation in cancer." (PMID 29848360, 2018). "Specifically speaking, SMYD3 was demonstrated to be a protein methyltransferase implicated in cancer development." (PMID 29029425, 2017). "Here, we show that SMYD3 modulates another hallmark of cancer, DNA repair, by stimulating transcription of genes involved in multiple steps of homologous recombination." (PMID 28630472, 2017). "Due to its tumor-growth-inducing role and association with poor prognosis SMYD3 has emerged as a key target for anti-cancer therapies." (PMID 28050603, 2017). "As an experiment to confirm the microarray results, qRT-PCR analysis of 17 putative target genes in HCT116 and three other cancer cell lines (CaCO2, J82 and T24) showed that SMYD3 knockdown caused 40–70% decreases in their mRNA levels." (PMID 26350217, 2015). "To elucidate the significance of PC4 with respect to SMYD3 transactivation, we next investigated PC4 localization at the FNBP1 and MFGE8 genes by ChIP assays employing cross-linked chromatin isolated from control and SMYD3-depeleted cancer cells." (PMID 26350217, 2015). "In fact, functional in vitro studies showed that SMYD3 knockdown was associated with growth inhibition, apoptosis and reduced migration/invasion potential in cancer cell lines of those tumors." (PMID 25980436, 2015). "We first tested whether pharmacologic inhibition of the SMYD3/CDCP1 signaling axis in cancer cells blunts paracrine activation of cancer-associated fibroblasts (CAFs)." (PMID 41301830, 2025). "The enzyme SMYD3 was the first lysine methyltransferase (KMT) to be linked to cancer etiology." (PMID 35819319, 2022). "Furthermore, SMYD3 expression is a key risk factor for esophageal, breast, bladder, and other cancers." (PMID 35610596, 2022). "Consequently, SMYD3 overexpression has been linked to increased proliferation, transformation, and metastasis of cancer cells." (PMID 34842655, 2021). "SMYD3 silencing may reduce the progression of advanced cancer rendering SMYD3 a potential therapeutic target for cancer patients with KRAS mutations." (PMID 34335697, 2021). "Overall, SMYD3 is a versatile coregulator of multiple oncogenic pathways, affecting processes associated with gene expression and protein transactivation through which it integrates cellular signals and promotes cancer development." (PMID 34503239, 2021). "SMYD3 oncogenic activity has been linked to proliferation, cell cycle regulation, increased migration and invasion of cancer cells through multiple mechanisms, including chromatin remodeling, regulation of gene expression and interaction with and methylation of non-histone proteins." (PMID 34503239, 2021). "In addition to regulating gene expression, SMYD3 has been shown to play a significant role in human cancer by modulating various key cancer-associated factors and therefore their related oncogenic pathways." (PMID 34503239, 2021).